LHX2 (LIM homeobox 2)
Description:
Acts as a transcriptional activator. Stimulates the promoter of the alpha-glycoprotein gene. Transcriptional regulatory protein involved in the control of cell differentiation in developing lymphoid and neural cell types (By similarity).
Synonyms: LH2; LH-2; hLhx2
Tractability: No criterion of Open Targets' tractability assessment is met for any kind of drug.
Gene: Protein-coding gene on chromosome 9 (124,001,670 to 124,033,301, forward strand). Ensembl gene ENSG00000106689.
Subcellular location: Nucleus
Subcellular location (Human Protein Atlas): Nucleoplasm
Pathways (Reactome):
Developmental Biology: Regulation of expression of SLITs and ROBOs
Sensory Perception: Expression and translocation of olfactory receptors
Gene Ontology:
Molecular function: protein binding; DNA-binding transcription factor activity, RNA polymerase II-specific; RNA polymerase II transcription regulatory region sequence-specific DNA binding; chromatin binding; DNA binding; DNA-binding transcription activator activity, RNA polymerase II-specific; RNA polymerase II cis-regulatory region sequence-specific DNA binding; sequence-specific DNA binding
Biological process: neuron differentiation; positive regulation of DNA-templated transcription; regulation of transcription by RNA polymerase II; negative regulation of gene expression, epigenetic; negative regulation of neurogenesis; positive regulation of neural precursor cell proliferation; positive regulation of transcription by RNA polymerase II; regulation of DNA-templated transcription
Cellular component: chromatin; nucleus
Genetic constraint (gnomAD): Loss-of-function variants: 6 observed, 32.16 expected, observed/expected ratio (o/e) 0.19, 90% interval 0.1 to 0.37. The upper end of that interval is the gene's LOEUF score, 0.37, which puts it in group 1 of 6, group 1 being the genes least tolerant of losing a copy. Missense variants: 442 observed, 575.75 expected, observed/expected ratio (o/e) 0.77, 90% interval 0.71 to 0.83. Synonymous variants: 292 observed, 248.42 expected, observed/expected ratio (o/e) 1.18, 90% interval 1.07 to 1.29.
Gene-disease validity (ClinGen):
ClinGen rates the evidence that LHX2 causes each of these diseases.
complex neurodevelopmental disorder (autosomal dominant): Strong. A disorder that involves more than one phenotype associated with the central nervous system, including but not limited to intellectual disability, autism, and seizures (epilepsy).
Homologues: Orthologues: chimpanzee LHX2 (100% identical), guinea pig LHX2 (99% identical), macaque LHX2 (99% identical), pig LHX2 (99% identical), dog LHX2 (99% identical), rabbit LHX2 (99% identical), mouse Lhx2 (99% identical), rat Lhx2 (99% identical), tropical clawed frog lhx2 (87% identical), zebrafish lhx2b (84% identical). Paralogues in human: LHX9 (69% identical), ZFHX3 (27% identical), LHX6 (26% identical), ZFHX4 (26% identical), LHX8 (26% identical), LHX5 (25% identical), LHX1 (24% identical), LMX1A (24% identical), LHX3 (23% identical), LMX1B (23% identical), ZFHX2 (22% identical), LHX4 (22% identical), and 8 more.
Diseases named in the same sentence as LHX2 in open-access papers:
LHX2 is named in the same sentence as 71 diseases in open-access papers, as found by Europe PMC text mining. Sharing a sentence is not in itself a finding about the gene and the disease. The quoted sentences say what the papers report.
breast carcinoma (13 papers, 2015 to 2024). "Immunohistochemistry and immunofluorescence assays helped to analyze LHX2-associated immune infiltration in breast cancer." (PMID 37345110, 2023). "Some breast cancer risk-associated genes such as LHX2, TFAP2B, JAKMIP1, and SEPT9 were differentially methylated in site-specific and differentially methylated region (DMR) analysis." (PMID 35743249, 2022). "Of the 43 differentially methylated genes associated with breast cancer risk in the individual CpG sites analysis of normal breast tissue main analysis, LHX2 was included in three DMRs, TFAP2B in two DMRs, JAKMIP1 in one DMR, and SEPT9 in one DMR." (PMID 33113958, 2020). "LIM homeobox 2 (LHX2) is an oncogene that promotes malignancy in breast cancer and pancreatic ductal adenocarcinoma." (PMID 39664521, 2024). "LHX2 was also highly expressed in HER-2-positive breast cancer and TNBC, which have more clinical benefits in immunotherapy than other subtypes of BRCA." (PMID 37345110, 2023). "Immunohistochemistry and immunofluorescence experiments were conducted to investigate LHX2-related immune infiltration in breast cancer tissues." (PMID 37345110, 2023). "Our study explored the prognostic value and the immune cell infiltration of breast cancer related to LHX2." (PMID 37345110, 2023). "In this study, we show that LHX2 is upregulated in breast cancer tissues and positively correlated with breast cancer progression." (PMID 37345110, 2023). "In vitro and in vivo experiments confirmed that LHX2 promoted cell proliferation, migration ability, and invasive ability but inhibited apoptosis in breast cancer." (PMID 37345110, 2023). "Meanwhile, the clinical characteristics of breast cancer and LHX2 expression showed a strong correlation." (PMID 37345110, 2023). "Through in vitro and in vivo experiments, we found that LHX2 promoted cell proliferation, invasion ability, and migration in breast cancer, whereas it suppressed apoptosis in breast cancer." (PMID 37345110, 2023). "Experiments showed that LHX2 promotes the proliferation, colony formation, migration, and invasion of breast cancer cells." (PMID 37345110, 2023). "To confirm the role of LHX2 in breast cancer, we detected the expression level of LHX2 in breast cancer cell lines, and the two cell lines with the highest LHX2 expression were selected for subsequent functional experiments." (PMID 37345110, 2023). "Our study further discussed the prognostic value of LHX2 in breast cancer and its related mechanisms." (PMID 37345110, 2023). "As the role of LHX2 in breast cancer has yet to be thoroughly illustrated, we concentrated on the prognostic value and immune infiltration of LHX2 in our study." (PMID 37345110, 2023). "The results show that the downregulation of LHX2 inhibited the cell proliferation of breast cancer in vivo." (PMID 37345110, 2023). "Immunohistochemistry, immunofluorescence, and a TUNEL assay were performed on these tumor tissues to explore the mechanism of LHX2 in breast cancer immune infiltration and apoptosis." (PMID 37345110, 2023). "For example, it was found that LHX2 promotes breast cancer oncogenesis by increasing the PDGF-B expression in breast cancer cells." (PMID 36011368, 2022). "The LHX2 gene exhibited significant methylation changes at two different CpG sites in breast cancer." (PMID 35743249, 2022). "LHX2 is reported to participate in oncogenesis and promote tumor growth in breast cancer and pancreatic ductal adenocarcinoma, suggesting the role of LHX2 in carcinogenesis and cancer progression." (PMID 34001679, 2021). "LHX2 promotes the growth and metastasis of nasopharyngeal carcinoma by regulating Wnt signaling; facilitates breast cancer metastasis through PDGF-B signaling; and is aberrantly expressed in lung cancer and pancreatic ductal carcinoma." (PMID 31724536, 2019). "Elevated expression of LHX2 was found in NSCLC cells, supporting the findings that LHX2 serves as a tumor promoter in breast cancer cells." (PMID 26189214, 2015).
breast carcinoma (continued). "Finally, we confirmed that LHX2 promoted the cell proliferation, migration ability, and invasion ability of breast cancer through in vitro and in vivo experiments." (PMID 37345110, 2023). "Taken together, LHX2 plays a vital role in breast cancer’s progression and prognosis and could be an immune infiltration biomarker for breast cancer, and LHX2 activates the PI3K/AKT/mTOR pathway and apoptosis pathway in breast cancer." (PMID 37345110, 2023). "We found that LHX2 can serve as an independent prognostic factor in breast cancer." (PMID 37345110, 2023). "Moreover, ssGSEA showed that Th1 cells and Th2 cells had a positive correlation with LHX2 expression in breast cancer." (PMID 37345110, 2023). "LHX2, a member of the LIM homeobox gene family and a transcription factor, plays a crucial role in numerous tumors, but the function of LHX2 in breast cancer progression remains unknown." (PMID 37345110, 2023). "In conclusion, the expression level of LHX2 is related to the immune infiltration of breast cancer." (PMID 37345110, 2023). "One gene, LHX2, harbored significant methylation changes at two different CpG positions, while 15 genes harbored significant methylation changes consistent with their differential expression in breast cancer." (PMID 33113958, 2020). "In the future, we may be able to carry out more experiments to study the deeper mechanism of LHX2’s regulation of breast cancer proliferation and migration and to also reveal how LHX2 is involved in the regulation of the tumor immune microenvironment of breast cancer." (PMID 37345110, 2023). "The Western blot results indicated that LHX2 activated the PI3K/AKT/mTOR pathway and apoptosis pathway in breast cancer, and it inhibited the apoptosis of BRCA." (PMID 37345110, 2023). "Moreover, we compared the expression of LHX2 in 1109 breast cancer tissue samples and 113 para-cancerous samples in the TCGA BRCA dataset, and we found that LHX2 expression was upregulated in breast cancer tissues compared to normal tissues." (PMID 37345110, 2023). "LHX2 has been reported to promote the proliferation of numerous solid tumors, but its role in breast cancer has not been elucidated." (PMID 37345110, 2023). "To establish whether LHX2 activates the PI3K/AKT/mTOR pathway and apoptosis pathway in breast cancer, we conducted a Western blotting assay to detect the signature proteins in these pathways, including PI3K, p-PI3K, Akt, p-Akt, Bcl-2, and Bax." (PMID 37345110, 2023). "Previous studies reported that LHX2 participates in the progression of breast cancer and non-small lung cancer." (PMID 31724536, 2019). "Importantly, the only regions that displayed a positive correlation between methylation and expression among the breast cancers in the TCGA database were four far-upstream or intragenic regions for the genes EN1, PITX2, APC and LHX2." (PMID 26510686, 2015). "Furthermore, immunohistochemistry and immunofluorescence experiments verified that LHX2 promoted the expressions of infiltrating T cells and CD4 + T cells in breast cancer, and a Western blot assay demonstrated that LHX2 activates the PI3K/AKT/mTOR pathway and apoptosis pathway." (PMID 37345110, 2023).
nasopharyngeal carcinoma (7 papers, 2019 to 2023). A carcinoma arising from the nasopharyngeal epithelium. "For instance, the overexpression of LHX2 promotes the development of chronic myeloid leukemia, pancreatic ductal carcinoma, nasopharyngeal carcinoma, and non-small-cell lung cancer." (PMID 37345110, 2023). "Inhibition of FGF1 with siRNA or FGFR inhibitor blocked LHX2-induced nasopharyngeal carcinoma cell growth, migration and invasion." (PMID 35864158, 2022). "Similarly, miR-506 attenuated tumor growth and metastasis via inactivation of the Wnt/β-catenin pathway by inhibiting LIM homeobox 2 (LHX2) in nasopharyngeal carcinoma." (PMID 33621206, 2021).
pancreatic ductal adenocarcinoma (7 papers, 2019 to 2024). An infiltrating adenocarcinoma that arises from the epithelial cells of the pancreas. "As for other LHX members, early studies revealed that LHX2 promoted tumor cell proliferation in pancreatic ductal adenocarcinoma, and LHX4 facilitated the development of colorectal cancer, both via enhancing Wnt/TCF4/β-catenin pathway." (PMID 31788020, 2019). "Similar to our results, it was previously shown that LHX2 silencing weakened the migration and invasion of non-small cell lung cancer (NSCLC), and LHX2 overexpression promoted cell proliferation by activating β-catenin/TCF signaling in pancreatic ductal adenocarcinoma." (PMID 36011368, 2022).
anemia (5 papers, 2006 to 2022). A reduction in the number of red blood cells, the amount of hemoglobin, and/or the volume of packed red blood cells. "While Lhx2 mutants are anophthalmic, display hypoplasia of the neocortex and severe anaemia, neuroretina specific loss of function of Lhx2 causes severe microphthalmia, loss of expression of a subset of retinal progenitor cell-specific genes, and ectopic expression of hypothalamic genes." (PMID 35269428, 2022). "The LHX2 has a critical role in hematopoiesis and Lhx2-null embryos die in utero with severe anemia." (PMID 35406494, 2022). "The LIM-homeobox gene Lhx2 is a candidate regulator of fetal hematopoiesis since it is expressed in the fetal liver and Lhx2−/− mice die in utero due to severe anemia." (PMID 18431502, 2008). "The mesenchymal defect in the liver of Lhx2-/- mice cause a lethal anemia, which is cell non-autonomous since the Lhx2-/- hematopoietic cells appears to be normal, suggesting that the mutant microenvironment is unable to support hematopoietic development." (PMID 16600034, 2006). "We have previously shown that the Lhx2-induced HPC lines self-renew by a cell nonautonomous mechanism, and the anemia in Lhx2-/- mouse embryos is due to a cell nonautonomous mechanism, suggesting that Lhx2 regulates genes encoding proteins involved in cell-cell interactions." (PMID 16600034, 2006).
osteosarcoma (5 papers, 2018 to 2024). A usually aggressive malignant bone-forming mesenchymal neoplasm, predominantly affecting adolescents and young adults. "For example, LHX2 is part of the mTOR signaling pathway in osteosarcoma, but has yet to be studied in placenta although the mTOR signaling pathway is known to be involved in nutrient transport in the placenta." (PMID 36622342, 2022). "In this study, we confirm that LHX2 is up-regulated in osteosarcoma, and that its silencing inhibits OS malignancy and induces autophagy via mTOR signaling." (PMID 31724536, 2019). "The carcinogenesis of LHX2 has been confirmed in osteosarcoma and prostate cancer." (PMID 35864158, 2022). "The transcript factor LHX2 is dysregulated in many cancers but its role in osteosarcoma (OS) remains unclear." (PMID 31724536, 2019). "Despite this knowledge, the role of LHX2 in osteosarcoma remains elusive." (PMID 31724536, 2019).
cervical cancer (4 papers, 2017 to 2022). A primary or metastatic malignant neoplasm involving the cervix. "LHX2 dysregulations have been detected in several cancers; the DNA methylation of LHX2 provided the potential value by serving as a novel biomarker in cervical cancer radiotherapy, but the role of LHX2 in ESCC remains ambiguous." (PMID 36011368, 2022).
chronic myeloid leukemia (4 papers, 2006 to 2023). "The cells engrafting the stem cell-deficient mice maintain high level of expression of Lhx2 in vivo, which eventually leads to a chronic myeloproliferative disorder resembling human chronic myeloid leukemia." (PMID 16600034, 2006). "Human chronic myeloid leukemia cells have been reported to express Lhx2 although its function in the disease is not clear." (PMID 16600034, 2006). "Another gene down-regulated after Lhx2 expression is turned off is Prkd2 (Protein kinase D2), which has also been shown to be a substrate for the BCR-ABL fusion protein present in chronic myeloid leukemia cells." (PMID 16600034, 2006).
Hepatic fibrosis (4 papers, 2006 to 2023). The presence of excessive fibrous connective tissue in the liver. "The deficiency LIM homeobox gene LHX2 developed liver fibrosis in mice and LHX2 negatively regulated hepatic stellate cell (HSC) activation." (PMID 37505679, 2023). "Lhx2-deficient mice develop progressive liver fibrosis during fetal development, indicating that LHX2 expression inhibits myofibroblastic changes in HSCs in mice." (PMID 30765795, 2019). "Chronic liver injury causes activation of hepatic stellate cells leading to hepatic fibrosis, and both Lhx2 and Csrp2 have been negatively implicated in this process, suggesting overlapping function of these genes also in non-hematopoietic cells." (PMID 16600034, 2006). "In Lhx2-deficient mice, formation of STM is not impaired in fetal livers, whereas the mice develop severe hepatic fibrosis during fetal development due to myofibroblastic changes in liver mesenchymal cells." (PMID 30765795, 2019). "In the liver, LIM homeobox 2 (LHX2), a transcription factor, is involved in mesoderm development and may function to inhibit the activation of hepatic stellate cells (HSC); such activation is essential to develop hepatic fibrosis and cirrhosis." (PMID 32050622, 2020).
Intellectual disability (4 papers, 2015 to 2025). "LHX2 also regulates brain development and is an activator of SOBP which has been observed to have strikingly specific expression in the limbic system, with disruption leading to abnormal cognition and intellectual disability." (PMID 27295951, 2016). "Interestingly, haploinsufficiency of LHX2 has been associated with non-specific NDD phenotype including ASD, variable intellectual disability, speech impairment and microcephaly, as well as behavioral, sleep and brain magnetic resonance imaging abnormalities." (PMID 40401629, 2025).
Anophthalmia (3 papers, 2010 to 2021). Absence of the globe or eyeball. "Anophthalmia, the most severe phenotype, is associated with mutations of the Rax, Sox2, Lhx2, BMP-4, and BMP7 genes." (PMID 31817535, 2019). "The LIM homeobox 2 (LHX2) transcription factor has been shown to be essential for mammalian eye development and mice deficient in functional Lhx2 protein have been shown to display anophthalmia." (PMID 21203406, 2010). "We hypothesize that mutations in LHX2 could lead to severe eye developmental disorders including micro/anophthalmia." (PMID 21203406, 2010). "However, probably due to the functional redundancy with lhx2 ortholog lhx2a in zebrafish, mutation of lhx2b does not induce anophthalmia." (PMID 33579692, 2021). "Mutations in LHX2 do not represent a frequent cause of micro/anophthalmia." (PMID 21203406, 2010).
microphthalmia (3 papers, 2019 to 2023). Congenital or developmental anomaly in which the eyeballs are abnormally small. "These anterior structures, including the vitreous, fail to form in the Lhx2-PE-cKO mice, further contributing to severe congenital microphthalmia." (PMID 36649236, 2023).
non-small cell lung carcinoma (3 papers, 2015 to 2023). A group of at least three distinct histological types of lung cancer, including non-small cell squamous cell carcinoma, adenocarcinoma, and large cell carcinoma. "They uncovered that miR-1238 inhibits non-small cell lung cancer (NSCLC) cell growth partly by repressing LHX2." (PMID 30946694, 2019). "We investigated the functional contribution of miR-1238 to the regulation of LHX2 in non-small cell lung cancer (NSCLC)." (PMID 26189214, 2015).
prostate carcinoma (3 papers, 2020 to 2022). A carcinoma that arises from epithelial cells of the prostate gland. "Among the 95 NLS genes, the expression of ARHGEF2, LHX2, and EPHB2 is close associated with clinicopathologic features and shortened disease-survival outcomes in prostate cancer patients." (PMID 36159187, 2022). "Among the 95 NLS genes, the expression of ARHGEF2, LHX2, and EPHB2 is close associated with shortened disease survival in prostate cancer patients." (PMID 36159187, 2022). "Collectively, these results suggest the potential of ARHGEF2, LHX2, and EPHB2 as indicators of poor survival for advanced prostate cancer." (PMID 36159187, 2022).
retinal degeneration (3 papers, 2013 to 2023). Degeneration of the retina. "We also cannot exclude the possibility that reactive Müller glia cells are also involved in hamartoma formation in Lhx2-Cre:Tsc1f/f mice, as was recently demonstrated for other rodent models of retinal degeneration." (PMID 26449264, 2015).